LINC01048 (long independently transcribed non-coding RNA 1048)
Gene: Long non-coding RNA gene on chromosome 13 (37,481,464 to 37,527,178, reverse strand). Ensembl gene ENSG00000230390.
Diseases named in the same sentence as LINC01048 in open-access papers:
LINC01048 is named in the same sentence as 1 disease in open-access papers, as found by Europe PMC text mining. Sharing a sentence is not in itself a finding about the gene and the disease. The quoted sentences say what the papers report.
cutaneous squamous cell carcinoma (1 paper, 2023). "For instance, LINC01048 increases the binding of TAF15 to YAP1 promoter and gives rise to sustaining activation of Hippo pathway and hence promotes cell proliferation in cutaneous squamous cell carcinoma." (PMID 37257820, 2023).